KLF6 (KLF transcription factor 6)
Diseases named in the same sentence as KLF6 in open-access papers (continued):
Sharing a sentence is not in itself a finding about the gene and the disease.
atherosclerosis (7 papers, 2020 to 2025). A disease characterized by the build-up of fatty material and calcium deposition in the arterial wall resulting in partial or complete occlusion of the arterial lumen. "Canonical Pathway analysis on genes significantly downregulated with the loss of KLF6 revealed significant inhibition of “Granulocyte Adhesion and Diapedesis” as well as “Atherosclerosis Signaling” pathways." (PMID 37437844, 2023). "KLF6 plays a significant role in vascular endothelial protection in atherosclerosis by inhibiting inflammation, oxidative stress, and monocyte adhesion." (PMID 41373858, 2025). "Another member of the KLF family, KLF6, regulates several genes involved in the development of atherosclerosis, including genes involved in inflammation, lipid metabolism, and vascular smooth muscle cell proliferation." (PMID 36984888, 2023). "In macrophages, KLF6 has been shown to play a protective role in the development of atherosclerosis." (PMID 36984888, 2023). "Further research into the role of KLF6 in atherosclerosis and the range of potential for naproxen as an anti-AS treatment is still necessary." (PMID 34427537, 2021). "Modulating the expression of KLFs including KLF6 is considered a potential treatment strategy for atherosclerosis." (PMID 33052879, 2020). "However, the downregulation of KLF6 promotes the generation of vascular protective M2 macrophages, attenuating atherosclerosis." (PMID 41373858, 2025). "KLF6 appears to be a key regulator of MØ inflammatory responses in the context of atherosclerosis." (PMID 40607379, 2025). "KLF6 is mainly expressed in endothelial cells and has been shown to mediate macrophage phenotype polarization, which plays a major role in the pathogenesis and regression of atherosclerosis." (PMID 33052879, 2020). "Subsequent functional annotation identified eight atherosclerosis-relevant candidate genes: transcription factors (KLF12, KLF6, KLF9, and MEF2C), epigenetic regulators (HDAC9), and signaling molecules (YAP1, SOCS6, and CDC25A)." (PMID 41373654, 2025).
diabetes (7 papers, 2014 to 2025). "All treated groups showed improvement of glycemic and lipid profiles and UACR with enhancement of renal KLF6 expression and improved histological architecture of diabetic kidney." (PMID 41191050, 2025). "In this study, we demonstrate that the podocyte-specific induction of KLF6 attenuates kidney injury in a murine model of diabetes." (PMID 39271683, 2024). "We identified 8 hub genes (JUN, ATF3, VEGFA, SLC2A1, HK2, PTGS2, PFKFB3, and KLF6) that were enriched in response to hypoxia, angiogenesis, vasculogenesis, hypoxia-induced signaling, cancer, diabetes, and transplant-related disease pathways." (PMID 36482897, 2022). "Additionally, KLF6 is a critical member of the KLF family involved in diabetes and diabetic complications." (PMID 34967261, 2022). "Concerning the potential role of LPIN1 rs13412852, KLF6 rs3750861, SOD2 rs4880, TM6SF2 rs58542926, and ZNF624 rs12603226 SNPs in glycemic control of the patients with diabetes, data are also limited." (PMID 34746177, 2021). "To identify differentially expressed genes (DEGs) in the setting of podocyte-specific KLF6 induction with and without diabetes, we initially performed differential expression analysis on all the clusters." (PMID 39271683, 2024). "In addition, in an in vivo study in diabetic rats, they showed that KLF6 and PPAR-γ (localized downstream of KLF6) play a key role in the regulation of TXNIP expression in the development of diabetes mellitus." (PMID 24397367, 2014).
glioma (7 papers, 2009 to 2024). A benign or malignant brain and spinal cord tumor that arises from glial cells (astrocytes, oligodendrocytes, ependymal cells). "The expression of miR-181a is increased in glioma, and miR-181a can inhibit Kruppel-like factor 6 (KLF6) mRNA expression by directly binding to the 3' UTR of KLF6 mRNA; KLF6 can promote the transcriptional expressions of ZO-1, occludin, and claudin-5 mRNAs." (PMID 33767583, 2021). "In glioma ECs, upregulation of miR-181a targeted Kruppel-like factor 6 (KLF6), downregulating ZO-1, occluding, and claudin-5, and increased permeability of the blood-tumor barrier (BTB)." (PMID 27999452, 2016). "KLF6 acts as a tumor suppressor in various solid cancers (colorectal, prostate, glioma), but may also support cancer progression in certain contexts." (PMID 38730619, 2024). "LINC00052 represses the proliferation, migration and invasion of glioma cells by upregulating KLF6." (PMID 33231561, 2020). "In addition, miR-181a-5p suppresses proliferation and induces apoptosis of glomerular mesangial cells by suppressing KLF6 and BCL2 expression via reduction of WNT/β-catenin signaling in human diabetic nephropathy and of glioma cell lines through suppression of the gene encoding for Cyclin B1." (PMID 33572377, 2021).
cervical carcinoma (6 papers, 2013 to 2024). A carcinoma arising from either the exocervical squamous epithelium or the endocervical glandular epithelium. "In cervical carcinoma, loss and/or mutation of KLF6 results in its inactivation and/or downregulation, contributing to cervical cancer pathogenesis via the effects on targeted genes that control cell proliferation and differentiation." (PMID 29152072, 2017). "Inhibition of ZFAS1 reduces cervical cancer tumor growth and the expression levels of KLF6 but increases the expression levels of miR-190a-3p." (PMID 35406713, 2022). "We found that KLF6 mRNA stability was altered in liver-derived cell lines as compared to cervical cancer-derived cell lines and human embryonic fibroblasts." (PMID 24378751, 2013). "Moreover, miR-190a-3p was decreased in cervical cancer, and play as a suppressor to repress invasion by targeting KLF6." (PMID 38500077, 2024). "Therefore, ZFAS1 could regulate cervical cancer pathogenesis by regulating the miR-190a-3p/KLF6 axis." (PMID 35406713, 2022). "Also, to evaluate whether such KLF6 role can be extended to tumoral contexts, we determined the rate of cellular senescence in the cervical carcinoma HeLa cell line, which was reported to express low levels of endogenous KLF6 protein." (PMID 31824948, 2019). "The discovery that KLF6 is a key target of platelet-derived TGF-β signaling in HeLa cells identifies a potential new therapeutic target for the prevention and treatment of cervical carcinoma." (PMID 29152072, 2017). "At the end of our study, based on the results in the NIH3T3 model, we overexpressed wild type KLF6 in HeLa cell line derived from human cervical carcinoma, but we did not overexpress any of the splice forms since they are not subject of study in the present brief report." (PMID 31824948, 2019).
colon cancer (6 papers, 2007 to 2025). "The infiltration levels of all TIICs, including B cells, CD4+T cells, CD8+ T cells, neutrophils, macrophages, and dendritic cells, were favourably linked with the expression of KLF3, KLF5, and KLF6 in colon cancer." (PMID 35345512, 2022). "Additionally, KLF6-SV2, an SV2 variant of one of the KLF6 selective splice isoforms, was discovered to be considerably inhibiting the proliferation of the colon cancer (SW480 and SW620 cell lines)." (PMID 36358661, 2022). "We further sought to understand the molecular mechanisms of certain critical DETFs, FOSL2 and KLF6, in FR colon cancer cells." (PMID 40082673, 2025). "In contrast, some ZFPs from the KLF family are aberrantly expressed in colon cancer and have proliferation inhibitory effects, such as KLF5, KLF4, KLF6, and KLF3." (PMID 36358661, 2022). "Further, among validated DEGs were those with established roles in colon cancer and CCSC (KLF6 and SQSTM1) and those with emerging roles (SPTLC2, SEC24D, and ACACA)." (PMID 34845203, 2021). "Moreover, relatively high coexpression scores were also observed for FOSL2/KLF6, FOSL2/RUNX2 and GRHL2/FOXA1, suggesting that the DETFs related to H3K23su DERs might work together and be responsible for 5-FU resistance in HCT15 colon cancer cells." (PMID 40082673, 2025).
melanoma (6 papers, 2020 to 2023). A malignant, usually aggressive tumor composed of atypical, neoplastic melanocytes. "Class II enhancers exhibit a heterogeneous mutation pattern wherein melanoma genomes can acquire different types of mutation in some functional loci (such as the non-coding region of KLF6)." (PMID 37904237, 2023). "Prior studies have reported that loss of KLF6 in collagen-rich environments leads to increased melanoma proliferation, which is consistent with the role of KLF6 as a tumor suppressor in multiple cancers." (PMID 37561850, 2023). "The miR-4262 can significantly reduce the expression of KLF6 protein and promote the proliferation of melanoma cells." (PMID 33821195, 2021). "hsa-miR-4262 was also expressed in five human melanoma cell lines, and its expression pattern was opposite to KLF6 expression." (PMID 33821195, 2021). "In light of our findings, it would be informative to examine the role of KLF6 inactivation in melanoma initiation and how the extracellular matrix could modulate this process." (PMID 37561850, 2023). "In melanoma, KLF6 overexpression reduced the expression of EGFR protein." (PMID 32552913, 2020). "Similar to our observations of KLF4 action in TNBC cells, KLF6 is a tumor suppressor that inhibits metastasis and the EGFR/AKT pathway in melanoma and lung adenocarcinoma." (PMID 32552913, 2020). "Similarly, PTEN, NF1, KLF6, and THBS1 genes were frequently reported in different cancer gene resources as melanoma tumor suppressors." (PMID 37904237, 2023).
heart failure (5 papers, 2013 to 2025). Inability of the heart to pump blood at an adequate rate to meet tissue metabolic requirements. "As well as Klf4, Klf6, and Klf9 showed an enriched expression in cells from patients with heart failure compared with the healthy human heart." (PMID 36082978, 2023). "In mammals, the regulation of autophagy by KLFs, including KLF2, KLF4 and KLF6, is also involved in vascular aging, heart failure, and cell aging." (PMID 37543362, 2023).
Obesity (5 papers, 2020 to 2024). Accumulation of substantial excess body fat. "Notably, associations with obesity-related SNPs have been reported separately for KLF6 and KLF7." (PMID 39272379, 2024). "Obesity upregulated the expression of Klf2, Klf4, Klf6 and Klf9 at all timepoints in heart art, cap and ven ECs." (PMID 36400935, 2022). "On the other hand, genes up-regulated with pregravid obesity enriched to GO terms associated with transcriptional regulation (JMJD1C, CHD1, HIF1A, TCF25, and KLF6)." (PMID 33912153, 2021). "The synteny between KLF6 and KLF7 may collectively regulate intramuscular fat deposition and obesity in the organism." (PMID 39272379, 2024). "Similarly, genes encoding circadian clock regulators (Dbp, Nr1d1 and Nr1d2), KLF transcription factors (Klf2 and Klf6) and cell signaling molecules (Rhob and Shank3) were also upregulated in sustained obesity (cohort 2) but not in the reversion group (cohort 3)." (PMID 36400935, 2022).
pancreatic cancer (5 papers, 2017 to 2024). "Second, the mechanisms underlying the impact of KLF6 on pancreatic cancer progression are still unknown." (PMID 38773440, 2024). "In pancreatic cancer cells, KLF6 was expressed higher in PATU-8988 and PANC-1 cell lines compared to others." (PMID 38773440, 2024). "Through single-cell RNA sequencing (scRNA-seq) analysis, we screened KLF6 and further investigated its biological functions in pancreatic cancer and pan-cancer." (PMID 38773440, 2024). "Although we developed a KLF_score to serve as a reliable predictor of pancreatic cancer prognosis and demonstrated the contribution of KLF6 to the development of the disease, our study has some limitations." (PMID 38773440, 2024). "Through single-cell RNA sequencing (scRNA-seq), we screened for KLF6 and explored its biological role in pancreatic cancer cells." (PMID 38773440, 2024). "The proliferation and metastatic capacity were significantly suppressed by the downregulation of KLF6 in pancreatic cancer cells." (PMID 38773440, 2024). "Further cellular analysis on KLF6 confirmed the role it plays in the malignancy of pancreatic cancer." (PMID 38773440, 2024). "KLF6 expression was highly elevated in pancreatic cancer samples compared to adjacent normal tissue samples." (PMID 38773440, 2024). "Subsequently, the transwell assays determined that KLF6 enhanced the migratory and invasive abilities in pancreatic cancer cells." (PMID 38773440, 2024). "Then, we investigated the prognostic value of KLF6 in pancreatic cancer by immunohistochemical assays." (PMID 36615000, 2022). "The role of KLF6 in proliferation and metastasis, as well as its potential mechanism in pancreatic cancer, were investigated as well." (PMID 36615000, 2022). "Our study identifies the tumor-suppressor role of KLF6 in pancreatic cancer, yet the role of splicing isoforms of KLF6 in pancreatic cancer needs further research." (PMID 36615000, 2022). "We also verified that KLF6 inhibits growth and metastasis in pancreatic cancer, indicating that KLF6 plays a tumor-suppressor role in pancreatic cancer." (PMID 36615000, 2022). "In this research, we found that KLF6 expresses lowly in pancreatic cancer samples and that survival analysis demonstrates that lower KLF6 expression is linked to a worse survival prognosis in PAAD." (PMID 36615000, 2022). "In this study, the expression pattern and the prognostic value of KLF6 in pancreatic cancer were explored." (PMID 36615000, 2022). "The results indicate that KLF6 is lowly expressed in tumor samples when compared to normal samples, and its expression is closely correlated with clinical prognosis in pancreatic cancer." (PMID 36615000, 2022). "Next, we sought to analyze KLF6 expression profiles and clinicopathologic features in an independent collection of pancreatic cancer samples." (PMID 36615000, 2022). "For example, KLF6 is the downstream target of miR-342-p in pancreatic cancer cells, whereby stable expression of KLF6 reduced the cancer cells’ viability and increased the sensitivity to gemcitabine." (PMID 32998281, 2020). "Our work investigated the essential role of KLF6 in pancreatic cancer." (PMID 36615000, 2022). "In a word, this study demonstrates that KLF6 inhibits the progression of pancreatic cancer through upregulating ATF3 and may serve as a potential therapeutic target." (PMID 36615000, 2022). "However, the specific and detailed molecular mechanisms of how ATF3 is regulated by KLF6 and other potential mechanisms in pancreatic cancer need more research." (PMID 36615000, 2022). "To determine whether KLF6 is involved in pancreatic cancer progression through ATF3, we performed rescue experiments." (PMID 36615000, 2022). "However, gaps still remain in our knowledge of the role of KLF6 in pancreatic cancer (PAAD)." (PMID 36615000, 2022). "Additionally, protein levels of KLF6 are markedly different among pancreatic cancer cells." (PMID 36615000, 2022).
pancreatic cancer (continued). "Furthermore, KLF6 can inhibit the progression of pancreatic cancer by upregulating ATF3." (PMID 36615000, 2022). "To further explore the relationship between KLFs and the prognosis of patients with pancreatic cancer, univariate Cox regression was performed, and we identified 4 significantly prognostic genes (KLF3, KLF4, KLF5, KLF6) with p < 0.05." (PMID 38773440, 2024). "As a result, overexpression of KLF6 in AsPc-1, CFPAC-1, and PANC1 cells decreases the growth of pancreatic cancer cells." (PMID 36615000, 2022). "Overexpression of KLF6 inhibits the proliferation, metastasis, and EMT progression in pancreatic cancer cells." (PMID 36615000, 2022). "We also observed the differential methylation of four pancreatic cancer marker genes, i.e., FOSB, KLF6, ATP4A, GSG1, related to survival of patients." (PMID 28423671, 2017). "We observed differential methylation of FOSB, KLF6, ATP4A, and GSG1 genes that are previously reported as markers for pancreatic cancer survival." (PMID 28423671, 2017). "Moreover, single-cell sequencing data revealed that KLF6 was strongly expressed in tumor immune cells, such as macrophages, indicating that KLF6 may participate in remodeling TIME, enhancing the progression of pancreatic cancer." (PMID 38773440, 2024). "However, the role of KLF6 in pancreatic cancer has not been identified." (PMID 36615000, 2022).
prostate tumor (5 papers, 2003 to 2022). "In the case of KLF6, it has been shown that a single germline DNA polymorphism is responsible for the generation of KLF6-v1 in prostatic tumors." (PMID 27323810, 2016). "Expression profiling analysis and modeling of transcriptional regulatory networks predicts a functional association between MYC and the prostate tumor suppressor KLF6." (PMID 18190704, 2008). "In a 2020 study, the authors investigated the MIR4435-2HG/miR-513a-5p/KLF6 axis, which upregulated in ccRCC KLF6, which is shown to be a typical suppressor of tumors of various localizations, including prostate tumors, colorectal tumors, etc.." (PMID 34681854, 2021).
steatosis (5 papers, 2018 to 2023). Increased lipid within the cytoplasm of cells. "The KLF6 gene was highly expressed in various tissues and played a critical role in adipocyte differentiation by activating PPARα that regulated hepatic steatosis, lipoprotein synthesis, hepatic gluconeogenesis and fatty acid transport proteins in mouse." (PMID 38017423, 2023). "KLF6 contributes to differentiation from nonalcoholic steatohepatitis to fibrosis from rat uncomplicated steatosis." (PMID 35672285, 2022). "A liver biopsy analysis of patients with NAFLD revealed that the elevated expression of full-length KLF6 was associated with advanced NAFLD, characterised by increased steatosis and fibrosis." (PMID 32998281, 2020). "But although both experimental and clinical findings suggest KLF6 promotes NASH, KLF6 levels correlate negatively with steatosis levels in NAFLD samples." (PMID 29942807, 2018). "Additionally, KLF6 deletion, either hepatocyte-specific or in all tissues, improved the insulin sensitivity and rendered protection against high-fat diet-induced steatosis via the post-transcriptional regulation of PPARα and its downstream targets." (PMID 32998281, 2020). "Further than the PNPLA3 and the TM6SF2 SNPs, we therefore tested the rs3750861 KLF6, the rs13412852 LPIN1, and the rs4880 SOD2 SNPs, which have demonstrated associations with fibrosis, steatosis and fibrosis, and again fibrosis, respectively, in previous studies on NAFLD patients." (PMID 29732362, 2018). "Although the reason for the conflicting observations is not immediately clear, expression of KLF6 and GCK may be differentially regulated in mild vs. advanced steatosis." (PMID 29942807, 2018).